MTOR (mechanistic target of rapamycin kinase)
Diseases named in the same sentence as MTOR in open-access papers (continued):
Sharing a sentence is not in itself a finding about the gene and the disease.
tumor (continued). "Similarly, previous research has demonstrated that necrotic tumor cells can elevate potassium ion (K +) levels in the tumor interstitial fluid, thereby impeding the mTOR-AKT-mediated effector program in CD8+ T cells and leading to their functional exhaustion." (PMID 37055849, 2023). "In addition, the hypoxia microenvironment and tumor mTOR signal can stabilize or induce the expression of HIF-1α, respectively, and HIF-1α can induce the expression of CD39 and CD73." (PMID 37834375, 2023). "Simvastatin can also inhibit CRC liver metastasis by reducing cholesterol biosynthesis because hepatocyte growth factor (HGF) released from the liver induces SREBP2 and activates the c-Met/PI3K/AKT/mTOR axis in tumor cells to increase the cholesterol biosynthesis." (PMID 38023258, 2023). "In these cases, one would possibly select a different drug that might target another part of the mTOR pathway or co-administer a second drug that interferes with the tumor metabolism of the rapalogues." (PMID 37240915, 2023). "Given the regulation at different levels of mTOR, PTEN, and ATF4 in FH-deficient tumours, it is tempting to speculate a potential link between these factors." (PMID 37689804, 2023). "Our candidate tumor suppressor p38 as well as its downstream targets such as phosphorylation of mTOR, actin remodeling and autophagy can be modulated with pharmacologically available small molecules such as anisomycin, rapamycin, hydroxychloroquine and cytochalasin." (PMID 36765834, 2023). "GEMM and allograft transplantation assays further confirmed that PI3K/mTOR inhibitors could effectively augment anti-tumor efficacy of IR." (PMID 37802999, 2023). "Overall, our collective findings offer valuable insights into the critical role of the ALKBH5/FABP5/FASN/mTOR axis in tumor progression and uncover a potential mechanism linking lipid metabolism to development of CRC, providing novel therapeutic targets for future interventions." (PMID 37416772, 2023). "For example, targeting most IGCTs with upregulated KIT/RAS/MAPK pathway and/or PI3K/AKT/mTOR pathway, designing inhibitors for these pathways may be a new idea for developing tumor-targeted drugs." (PMID 38012690, 2023). "Moreover, these processes promote mTOR activity to engage in protein synthesis in cancer cells, promote tumor growth, and control cellular responses by suppressing autophagy." (PMID 37762259, 2023). "In tumor cells, mTOR inside the nucleus may act as an oncogene and play a role in the regulation of transcription, apoptosis, and mitochondrial oxidation." (PMID 37176048, 2023). "As an important component of tumor metabolic reprogramming, glutamine metabolic reprogramming plays an important role in maintaining tumor cell energy homeostasis, ROS balance, and the continuous activation of mTOR." (PMID 36902385, 2023). "Notably, we identified one Chinese EC patient with a deleterious germline variant in the STK11 gene, a known tumor suppressor gene associated with the AMPK and mTOR pathway." (PMID 37730563, 2023). "After Co-Sp treatment, PI3K, AKT, and mTOR phosphorylation was down-regulated in tumor tissues." (PMID 37313467, 2023). "Inhibiting PI3K and mTOR has shown promising results in combating tumor cells." (PMID 37822691, 2023). "Finally, we further clarified the role of mTOR-HIF-1α-CCL8 in pro-tumor effect by TAMs through in vitro and in vivo experiments." (PMID 37884960, 2023). "It is clear that the modulation of mTOR signaling in the tumor microenvironment has significant effects on T-cell metabolism and function; thus, the accurate understanding of how targeting tumor cells alter T-cell immunity may be helpful." (PMID 36624636, 2023). "Several mTOR inhibitors have been widely applied for tumour treatment." (PMID 36750558, 2023). "Consequently, tumor cell metabolism can be influenced by the interaction with mTOR signaling and its ubiquitination." (PMID 37190313, 2023).
tumor (continued). "DT2216 might be able to reduce the immunosuppressive effect of mTOR inhibition in part via depleting tumor-infiltrating regulatory T cells (TI-Tregs) as shown in our recent study." (PMID 36588105, 2023). "The detailed mechanisms underlying leucine’s promotion effect on PC may involve the activation of mTOR signaling and the promotion of tumor-related inflammation." (PMID 37954977, 2023). "Activation of the mTOR pathway promotes the proliferation of tumor cells." (PMID 37569808, 2023). "According to other research findings, combining PI3K/AKT/mTOR inhibitors with ICIs (which include PD-1 inhibitors in parallel with CTLA-4 inhibitors) or other anti-tumor immunotherapy may enable patients to obtain the best efficacy." (PMID 38008753, 2023). "Also, mTOR inhibition has shown anti-angiogenic effects by suppressing the formation of new blood vessels crucial for tumor sustenance." (PMID 37834408, 2023). "The consumption of glucose by tumor limits T-cell metabolism, leading to the dampened glycolytic capacity, mTOR activity, and IFN-γ production, representing the adaptation of resistance to the MSI-induced immunoreactive microenvironment and thereby allowing tumor progression." (PMID 37182124, 2023). "mTOR consists of two major complexes, mTOR complex 1 (mTORC1) and 2 (mTORC2), and is involved in multiple signalling pathways known to be activated in many types of tumours." (PMID 36983607, 2023). "We treated human TC cells (K1, MDA-T68, MDA-T32, TPC1) with (1S,3R)-RSL3 (RSL3), a small-molecule inhibitor of GPX4 and examined the effects on ferroptosis, tumor cell survival and migration, spheroid formation, oxidative stress, DNA damage repair response, and mTOR signaling pathway in vitro." (PMID 36371529, 2022). "Thus, in this study, we determined if the PI3K/AKT/mTOR pathway plays an important role in CAMK1D regulation of tumor function." (PMID 35494053, 2022). "mTOR inhibition in tumor cells has been shown to impact metastatic colonization and tumor growth." (PMID 35158337, 2022). "The mTor (p = 5.74e−17) and WNT (p = 2.44e−16) pathways were also more highly activated on tumor-side, which may be associated to the uncontrolled proliferation." (PMID 35332177, 2022). "Furthermore, upregulation of METTL14 mediates cisplatin resistance through activating the AMPKα/ERK1/2/mTOR pathway to reduce autophagy and apoptosis, resulting in accelerated tumor proliferation and metastasis." (PMID 35794625, 2022). "Further analysis of data from SUMMIT patients with HER2-mutant tumors across multiple tumor types revealed that mTOR pathway alterations were associated with a lack of clinical benefit with single-agent neratinib." (PMID 36627899, 2022). "The results showed the drug-resistant mice injected with EVs and cisplatin exhibited significantly elevated miR-18a-5p, diminished NACC1 mRNA, p-AKT, and p-mTOR, and reduced tumorigenesis ability, tumor volume and weight (all P < 0.01), and decreased number of lung metastatic nodules." (PMID 35672774, 2022). "We further investigated the status of the PI3K/AKT/mTOR pathway in tumor tissues." (PMID 35354382, 2022). "Pro-tumor: Promotion of M2 TAM polarization via PI3K/Akt/mTOR signaling in HNSC." (PMID 36686729, 2022). "More recent studies confirm the interaction of the telomerase with various intracellular signaling pathways including the PI3K/AKT/mTOR pathway, which mainly participates in inflammation, the epithelial-to-mesenchymal transition, and tumor cell invasion and metastasis." (PMID 36557983, 2022).
tumor (continued). "Interestingly, the double mTOR/DNA-PKcs inhibitor CC-115 was well-tolerated by the zebrafish larvae, and it significantly decreased the tumor burden in the UM zf-PDX." (PMID 35804957, 2022). "In these areas of the tumor, mTOR is deactivated, inducing the autophagy process; conversely, reactivation of mTOR inhibits autophagy, so there exists an inverse relationship between mTOR signaling and autophagy." (PMID 35456001, 2022). "In addition, SB365 also suppresses the proliferation of human colon cancer cells and induces apoptosis by inhibiting the AKT/mTOR signaling pathway, leading to the suppression of tumor growth and angiogenesis." (PMID 35606807, 2022). "mTOR/AKT/PI3K pathway plays a central role in tumor oncogenesis and development." (PMID 36139607, 2022). "Consistently, several studies reported that resveratrol has an anti-tumor effect via Akt and mTOR." (PMID 36500361, 2022). "The increase in OGG1 was detected in several tumor cells treated to suppress mTOR activity." (PMID 35269445, 2022). "In ovarian cancer, the overexpression of HVEM (TNFRSF14), a member of the TNF receptor superfamily, is associated with the activation of AKT/mTOR signaling, promoting the expression of Bcl-2 and HIF-1α, which is positively associated with tumor proliferation and negatively related to cell apoptosis." (PMID 36358792, 2022). "In up to 50% of HCCs, the mammalian target of rapamycin (mTOR) signaling are aberrantly hyperactivated to drive tumor progression by underwriting biosynthetic programs and promoting proliferation 3-5, which is associated with a poor prognosis, poor differentiation and earlier recurrence." (PMID 36451866, 2022). "IL-7R, mTOR and tumor stage are the strongest predictor of survival." (PMID 35778432, 2022). "Indeed, the mTOR inhibitor rapamycin suppresses tumor angiogenesis by downregulating VEGF/VEGFR2 levels through the inhibition on translation initiation." (PMID 35053325, 2022). "LINC01554 is a novel tumor suppressor that could suppress tumorigenicity in HCC via Akt/mTOR signaling pathway." (PMID 35840618, 2022). "However, our study is the first that used MHY1485 for anti-tumor stem cells purposes and confirmed that mTOR can suppress CSCs, by inhibiting the autophagic process." (PMID 35406578, 2022). "As the Akt/mTOR axis, a canonical negative regulatory pathway for autophagy induction, is also correlated with tumor proliferation 16, we questioned whether Akt/mTOR axis is required for OXI-regulated autophagy initiation." (PMID 35813474, 2022). "mTOR, the catalytic subunit of both mTORC1 and mTORC2 complexes, is an important effector of metabolic change in NK cells, but is also a target of several tumor therapies." (PMID 35414042, 2022). "Furthermore, SSDs exert their anti-tumor effects through modulating PI3K/Akt/mTOR and Ras/Raf/MAPK pathways, preventing BC development." (PMID 36139460, 2022). "The dysregulation in the PI3K/PTEN/Akt/mTOR pathway also promotes the metabolic shifting to glycolysis, thus reducing the efficacy of 5-FU by decreasing its absorption, due to acidification of the tumour microenvironment, as well as hindering cell apoptosis." (PMID 35326689, 2022). "Moreover, insulin is also capable of downregulating AMPK pathway and upregulating mTOR pathway to inhibit metabolism and mitosis of tumor cells and selectively killing tumor stem cell." (PMID 35296101, 2022). "Because somatostatin analogue sensitizes tumor cells to mTOR inhibition and can also reverse resistance to mTOR inhibition through its inhibition of Akt, we expect that the combination of pasireotide long-acting release (LAR) and everolimus will result in even greater antitumor efficacy." (PMID 35681620, 2022). "Capsaicin can downregulate the mTOR signaling pathway of tumor cells." (PMID 36510333, 2022). "Additionally, miR-140 inhibited mTOR signaling and integrated upregulation of miR-140 with mTOR signaling exhibits exceptional synergistic anti-tumor effect." (PMID 36430305, 2022).
tumor (continued). "Moreover, increased lactate generation enhances the tumor-promoting capacity of MDSCs through the G protein-coupled receptor 81 (GPR81)/mTOR/HIF-1α/STAT3 pathway in PDAC." (PMID 36200045, 2022). "Activation of the PI3K/Akt/mTOR pathway leads to tumor development and anticancer drugs resistance." (PMID 36506551, 2022). "mTOR pathway plays the central role in tumor progression of GBC." (PMID 35484565, 2022). "For optimal tumor control it seems to be important to avoid immunosuppressive escalations due to rejection episodes and to maintain instead effective but low immunosuppressive levels, preferable with an mTOR inhibitor-based regimen." (PMID 35681642, 2022). "Considering the fundamental role of mTOR in tumor progression, it may serve as an important therapeutic target." (PMID 35579750, 2022). "Indeed, inhibitors of PI3K, Akt, and mTOR have been extensively studied at the preclinical level, and some have been used in clinical settings for in different tumor types." (PMID 36496978, 2022). "AKT1 is involved in regulating PI3K/AKT/mTOR, a tumor-generating pathway." (PMID 35603567, 2022). "In addition, the PI3K/Akt/mTOR pathway showed a strong correlation with the autophagy ability of tumor cells in our study, so we also detected the autophagy-associated proteins in HepG2 and found notable decrease of autophagy ability in HepG2." (PMID 36245984, 2022). "As MEN1 and PTEN co-mutation has been described in a limited number of PanNETs, it was found that menin and PTEN inhibition of the mTOR/AKT/PI3K pathway may cooperate to prevent tumor proliferation." (PMID 36139607, 2022). "As such, the PD-L1 expression in cancer cells can directly regulate tumor metabolism through Akt/mTOR signaling, independently of the PD-1 engagement, therefore upregulating tumor glycolysis that leads to microenvironment glucose deprivation and lactic acid concentration." (PMID 35211121, 2022). "Although Rictor is frequently increased in various human tumors and exerts different functions in an mTOR-dependent or -independent manner leading to tumor growth and increased invasive characteristics, the mechanisms regulating Rictor expression remains poorly understood." (PMID 35982899, 2022). "The PI3K/AKT/mTOR signaling pathway has protumoral effects that result in tumor progression." (PMID 35053485, 2022). "Thus, the antitumoral activity of mTOR-inhibitor-based therapies in pretreated tumor patients was weak." (PMID 35454843, 2022). "The activation of mTOR has been found to promote tumor growth and metastasis." (PMID 35645799, 2022). "Additionally, the combined targeting of mTOR and PD-L1 has been shown to enhance tumor growth suppression in a syngeneic mouse model of oral cancer." (PMID 36428613, 2022). "Moreover, CDK16 can promote tumor progression by regulating the mammalian target of rapamycin (mTOR) pathway." (PMID 34687270, 2022). "Comparable to mTOR, the expression of Erk1/2 also increased with the addition of tumor cells." (PMID 36552039, 2022). "The PI3K/Akt/mTOR pathway is involved in some neurodegenerative and tumor processes; moreover, mTOR has a significant role in the modulation of autophagy induction and is inversely related to SIRT1 (the latter is involved in neurodegenerative and tumor processes)." (PMID 35741059, 2022). "Therefore, the mTOR inhibitors sirolimus and everolimus are important drugs that reduce tumor size and suppress disease." (PMID 36011051, 2022). "In support of this hypothesis, rapamycin increases the phosphorylation of AMPK, a signaling intermediate upstream of the mTOR pathway in several tumor cells." (PMID 35269445, 2022). "In a different study, SCFAs could enhance CAR T cell anti-tumor activity via mTOR activation and the production of effector molecules, including TNF-α." (PMID 36358860, 2022). "Further addition of mTOR inhibitor (AZD8055) enhanced the tumor suppression." (PMID 36232388, 2022).
tumor (continued). "Paired analyses of the patient-matched primary tumor and BM has implicated that the activation of the PI3K/AKT/mTOR pathway and cyclin-dependent kinase (CDK) pathway may represent a site-specific contributor to BM development." (PMID 35644609, 2022). "PI3K Akt signaling pathway activation and tumor resistance are closely related, and the application of this pathway inhibitor, such as PI3K inhibitor, Akt inhibitor, and mTOR inhibitor, can reverse the resistance of tumor cells and restore the sensitivity of tumor cells to chemotherapeutic drugs." (PMID 35866054, 2022). "mTOR was reported to mediate drug resistance when activated in diverse tumor." (PMID 36214762, 2022). "Consistently, a study reported that specifically targeting PD-L1 with monoclonal antibodies resulted in decreased glycolysis in tumor cells via an obstruction of the PI3K/Akt/mTOR pathway and the translation of glycolytic enzymes, thereby improving the anti-tumor function of T cells." (PMID 36354714, 2022). "In addition, a series of novel inhibitors have shown high anti-tumor activity in clinical studies, and the use of anti-tumor drugs inhibiting mTOR in combination with other anti-tumor drugs has significant effects." (PMID 36558112, 2022). "Tumors in Pb-Cre4;Ptenf/f mice may be less sensitive to insulin/tumor-extrinsic CAMKK2 functions since there is already high basal mTOR signaling." (PMID 35741020, 2022). "Tumor heterogeneity in humans impacts the immunoexpression of proteins in the mTOR pathway in PC, and the decrease in mTOR immunoexpression is considered a late event after tumor progression, being associated with worse clinical and oncological outcomes in patients." (PMID 35681707, 2022). "PTEN acts as a potent tumor suppressor within the PI3K/AKT/mTOR pathway." (PMID 36039910, 2022). "The expression profiles of mTOR differed in different types of tumor tissues." (PMID 35082928, 2022). "Specifically, a study uncovered that Cyclin G1 up-regulates the expression of SOX2 by activating the Akt/mTOR signaling pathway, which leads to an increased proportion and enhanced tumor-initiating capacity of liver TICs, as well as inducing chemoresistance of HCC cells to sorafenib." (PMID 35267473, 2022). "Also, signatures reflecting oncogenic signalling such as MYC, KRAS, PI3K/mTOR and Notch, were enriched in the tumours of the young." (PMID 35995935, 2022). "Collectively, these results suggest that Ag120 exhibits a significant anti-tumor effect in CRC that may be mediated by inhibition of the mTOR and ERK1 signaling pathways." (PMID 35418865, 2022). "In addition to the role of Akt, Erk1/2 and mTOR pathways in tumor transition as well as CD24 and its influence on immune competence in the TME were analyzed." (PMID 36552039, 2022). "CAFs in lung induce high expression of SCD1 in tumor cells through PI3K/Akt/mTOR pathway, which enhances the ability of tumor cells to metastasize and may be related to lung metastasis of colon cancer or breast cancer." (PMID 36172157, 2022). "Additionally, drugs targeting the PI3K/AKT/mTOR pathway in combination with chemotherapy drugs or other targeted drugs can inhibit tumor development." (PMID 35402264, 2022). "Levels of p-AKT and p-mTOR were reduced in the tumor tissues." (PMID 35682990, 2022). "Furthermore, studies show that activation of PI3K-Akt-mTOR enhanced tumor cell tolerance to chemotherapy." (PMID 35022057, 2022). "The tumor-inhibiting effect of PLK2 might also be related to the mammalian target of rapamycin (mTOR) signaling pathway." (PMID 35898867, 2022). "This could prevent mTOR inhibition and accelerate the tumor growth of AMLs to a detectable size on imaging at an early stage." (PMID 35145067, 2022). "Finally, the importance of the interaction between the PI3K/AKT/mTOR signalling pathway and tumour suppressor/oncogenic miRNAs in NPC is presented." (PMID 35883139, 2022).